DUXAP8 (double homeobox A pseudogene 8)
Diseases named in the same sentence as DUXAP8 in open-access papers (continued):
Sharing a sentence is not in itself a finding about the gene and the disease.
breast cancer (5 papers, 2021 to 2025). A primary or metastatic malignant neoplasm involving the breast. "In addition, DUXAP8 exhibited overexpression in breast cancer and demonstrated association with poor prognosis, including radiation resistance." (PMID 40142329, 2025). "The lncRNA DUXAP8, transcribed from a pseudogene, modulates both the P3K/AKT/mTOR pathway and the EZH2-E-cadherin/RHOB pathways to exert its role in inducing breast cancer radioresistance." (PMID 39346726, 2024). "Furthermore, here for the first time we canvassed the literature to show that the expressed pseudogenes such as DUXAP8 are relevant not just to breast cancer but to radiotherapy against breast cancer." (PMID 39346726, 2024).
liver cancer (5 papers, 2021 to 2023). An epithelial or non-epithelial malignant neoplasm that arises from the liver. "LncRNA DUXAP8, which is highly expressed in liver cancer and associated with poor prognosis, contributes to sorafenib resistance through suppression of ferroptosis." (PMID 37337470, 2023). "In this study, it was found that DUXAP8 was highly expressed in liver cancer tissues and cells, where high expression of DUXAP8 often predicts poor prognosis in patients." (PMID 34957112, 2021). "In terms of the diagnostic value in liver cancer, the expression of MMP9, MIR4435-2HG, and DUXAP8 has the potential to differentiate between normal individuals and HCC patients." (PMID 35201491, 2021). "In summary, lncRNA DUXAP8 may be used in combination with sorafenib to achieve a higher anti‐liver cancer efficacy by acting on the SLC7A11‐mediated ferroptosis pathway." (PMID 37337470, 2023).
neuroblastoma (5 papers, 2021 to 2024). Neuroblastoma (NB) is the most common solid, extracranial childhood tumor. "According to the GEO database (GSE12460) and clinical data, high expression of DUXAP8 is associated with advanced neuroblastoma, and DUXAP8 expression is negatively correlated with overall survival in neuroblastoma patients." (PMID 35592755, 2022). "The lncRNA double homeobox A pseudogene 8 (DUXAP8) also activates the Wnt/β-catenin pathway in neuroblastoma." (PMID 38891878, 2024). "The stable knockdown of DUXAP8 inhibits the growth of neuroblastoma and decreases the expression of proteins related to the Wnt pathway, including β-catenin, c-Myc, and cyclin D1." (PMID 38891878, 2024). "Levels of DUXAP8 detected in neuroblastoma tumor tissues have been higher in T4 stage than in T1 stage, and elevated DUXAP8 expression is associated with worse prognosis." (PMID 34631702, 2021). "Studies have also revealed that DUXAP8 is substantially upregulated in neuroblastoma and papillary thyroid carcinoma tissues compared to corresponding adjacent normal tissues." (PMID 34631702, 2021).
papillary thyroid carcinoma (5 papers, 2021 to 2025). "There are other studies that regulate thyroid cancer with similar signaling pathways, such as lncRNA DUXAP8 promotes the cell proliferation, migration, and invasion of papillary thyroid carcinoma via miR-223-3p mediated regulation of CXCR4." (PMID 35264071, 2022). "In particular, DUXAP8 is upregulated and promotes cellular proliferation in papillary thyroid carcinoma and triple negative breast cancer." (PMID 35287542, 2022). "A recent study suggested that DUXAP8 accelerates cellular proliferation of papillary thyroid carcinoma via the ceRNAs mechanism." (PMID 35287542, 2022).
acute myeloid leukemia (3 papers, 2021 to 2025). Acute myeloid leukemia (AML) is a group of neoplasms arising from precursor cells committed to the myeloid cell-line differentiation. "In terms of leukemia, only a related paper is available, which observes that lncRNA DUXAP8 regulates acute myeloid leukemia glycolysis and apoptosis through the Wnt/β-actin pathway." (PMID 35311115, 2022). "lncRNA DUXAP8 inhibits glycolysis via suppression of the Wnt/β-catenin pathway in acute myeloid leukemia (AML)." (PMID 41361062, 2025).
colon cancer (3 papers, 2021 to 2025). "Elevated DUXAP8 expression has been identified as an indicator of unfavorable prognosis in colon cancer." (PMID 40556338, 2025). "In another report, high expression of DUXAP8 was found to predict poor prognosis in colon cancer." (PMID 40556338, 2025). "For example, a study revealed that DUXAP8 targeted miR-577 and promoted the expression of oncogene RAB14, which promoted colon cancer cell proliferation and progression." (PMID 38808892, 2024). "Based on survival analysis, it was found that high expression of DUXAP8 and ELFN1-AS1 predicts poor prognosis in colon cancer." (PMID 33959151, 2021).
esophageal cancer (3 papers, 2018 to 2021). A primary or metastatic malignant neoplasm involving the esophagus. "Genome-wide analysis showed that DUXAP8 was not only differentially expressed in esophageal cancer but was a diagnostic and therapeutic target for cancer." (PMID 32922554, 2020). "In this study, we analyzed two upregulated lncRNAs DUXAP8 and LINC00460 co‐expressed PCGs in esophageal cancer, and found that DUXAP8 associated PCGs are enriched in cell division and cell cycle, while LINC00460 associated PCGs are enriched in focal adhesion and cell‐cell junction processes." (PMID 29926523, 2018). "In esophageal cancer, DUXAP8 expression level is closely related to clinical stage, lymph node metastasis, and overall survival." (PMID 34631702, 2021). "GO enrichment analysis for DUXAP8 and its co-expressing PCGs showed that they were enriched in the cell cycle, cell division and DNA repair, suggesting an important role in the tumorigenesis and progression of esophageal cancer." (PMID 32922554, 2020). "A genome-wide analysis revealed that DUXAP8 was highly expressed in esophageal cancer." (PMID 32922554, 2020). "Further experimental validation revealed that knockdown of DUXAP8 could impair esophageal cancer cells proliferation and invasion in vitro." (PMID 29926523, 2018). "Similarly, we also found that knockdown of DUXAP8 could impair esophageal cancer cells proliferation and invasion, and DUXAP8 expression is positively related to oncogenes MAGEA4 and GABRA3 expression, but negatively related to tumor suppressors INPP5A and TIMP4." (PMID 29926523, 2018). "Interestingly, these pathways are closely associated with tumor cells proliferation and invasion, suggesting that DUXAP8 and LINC00460 might play important roles in esophageal cancer tumorigenesis and progression." (PMID 29926523, 2018). "Furthermore, DUXAP8 is positively related to MAGEA4, GABRA3 expression, and negatively related to INPP5A, TIMP4 expression in esophageal cancer; LINC00460 is positively related to ITGA3, LAMC2 expression, and negatively related to FOXO4, KLF15 expression in esophageal cancer." (PMID 29926523, 2018).
ovarian carcinoma (3 papers, 2021 to 2025). A malignant neoplasm originating from the surface ovarian epithelium. "DUXAP8 was found to be significantly overexpressed in ovarian cancer (OCa) tissues and cell lines, and its high expression correlated with poor patient prognosis." (PMID 40556338, 2025). "In a previous study, DUXAP8 was reported to promote the proliferation, migration and invasion of ovarian cancer cells." (PMID 37349838, 2023). "In addition, DUXAP8 has been shown to regulate the proliferation and apoptosis of ovarian cancer cells by targeting miR-590-5p." (PMID 37349838, 2023).
lung adenocarcinoma (2 papers, 2021). A carcinoma that arises from the lung and is characterized by the presence of malignant glandular epithelial cells. "Moreover, The Cancer Genome Atlas (TCGA) database showed that DUXAP8 in lung adenocarcinoma patients (LUAD) was significantly higher than in noncancerous tissue, and the level of DUXAP8 upregulation was associated with poor prognosis and reduced survival." (PMID 34235076, 2021).
oral cancer (2 papers, 2021). "DUXAP8 is substantially upregulated in oral cancer tissues compared to normal tissues." (PMID 34631702, 2021).
thyroid cancer (2 papers, 2021 to 2022). "GEPIA analysis indicated the positive relationship between high expression of DUXAP8 and the poor prognosis of thyroid cancer." (PMID 33522355, 2021). "GEPIA analysis results indicated the relationship between DUXAP8 and the prognosis of thyroid cancer." (PMID 33522355, 2021). "Also, we found through public database analysis that the high expression of lncRNA DUXAP8 was related to the poor prognosis of thyroid cancer." (PMID 33522355, 2021).
endometrial cancer (1 paper, 2021). Primary or metastatic malignant neoplasm involving the endometrium (mucous membrane that lines the endometrial cavity). "Little knowledge is currently available on the role of DUXAP8 in endometrial cancer." (PMID 34868993, 2021).
kidney cancer (1 paper, 2019). Primary or metastatic malignant neoplasm involving the kidney. "Moreover, our results suggested that DUXAP8 and DUXAP9 and other components in this pathway possessed significant prognostic values in patients with kidney cancer." (PMID 31409759, 2019). "Higher expression of DUXAP8 and DUXAP9 indicated poorer prognosis of kidney cancer." (PMID 31409759, 2019).
kidney neoplasm (1 paper, 2021). A benign or malignant neoplasm affecting the kidney. "For example, recent studies have found that CDKN2B-AS1 can be used as a biomarker for poor prognosis of kidney neoplasms, DUXAP8 enhances the progression of kidney neoplasms by downregulating miR-126, and HOTAIRM1 is downregulated in kidney neoplasms and inhibits hypoxia." (PMID 35058974, 2021).
lymph node metastasis (1 paper, 2021). "In colon cancer research, elevated DUXAP8 expression has been positively correlated with advanced stages, lymph node metastasis, and shorter overall survival time." (PMID 34631702, 2021).
melanoma (1 paper, 2021). A malignant, usually aggressive tumor composed of atypical, neoplastic melanocytes. "In contrast, A2058-specific SFPQ-enriched lncRNA included LINC00511, DUXAP8, TMEM51-AS1, FOXD2-AS1 and LINC01234, all of which have been shown to drive metastasis in a range of cancers via various mechanisms, however, only FOXD2-AS1 has been associated previously with melanoma." (PMID 34218270, 2021).
preeclampsia (1 paper, 2024). Preeclampsia is a hypertensive disorder of pregnancy that is characterized by new-onset hypertension with proteinuria presenting after 20 weeks of gestation, and depending on mild or severe forms may initially present with severe headache, visual disturbances, and hyperreflexia. "Additionally, Xiao-Hong Wei and others have discovered that the long non-coding RNA (lncRNA) DUXAP8 is upregulated in the placental tissues of patients with preeclampsia and is significantly correlated with multiple clinical indices." (PMID 39521940, 2024).
pulpitis (1 paper, 2024). Inflammation of the dental pulp. "DUXAP8 is mainly found in the hDPC cytoplasm and is highly expressed in tissues of pulpitis from patients and in the in vitro pulpitis model using LPS-hDPCs." (PMID 39769365, 2024). "Thus, increased expression of DUXAP8 can promote apoptosis, inflammation and oxidative stress in pulpitis through negative regulation of miR-18b-5p, generating augmented levels of HIF3A." (PMID 39769365, 2024). "Identification of additional targets of DUXAP8 establishing ceRNA networks could help to more clearly explain the different biological effects modulated by this lncRNA to propose possible applications in the treatment of pulpitis." (PMID 39769365, 2024).
renal cell adenocarcinoma (1 paper, 2021). A carcinoma arising from the renal parenchyma. "The lncRNA DUXAP8 was found upregulated in resected ccRCC tissue and human RCC cell lines 786-O and A498 cells (respectively derived from male and female renal cell adenocarcinoma epithelium), compared to normal kidney tissues." (PMID 33920158, 2021).
testicular germ cell tumor (1 paper, 2021). A germ cell tumor arising from the testis. "We also observed low DUXAP8 TPM in acute myeloid leukemia (LAML) and testicular germ cell tumors (TGCT) compared to normal tissues." (PMID 34631702, 2021).
tumor (42 papers, 2017 to 2026). "DUXAP8, which is overexpressed in > 60% of high-risk NB tumors, accelerates tumor progression via dual mechanisms: sequestering miR-29 to derepress NOL4L-mediated cell cycle activation and enhancing metastatic potential through TWIST1 stabilization." (PMID 40787450, 2025). "The L3 subtype showed a worse prognosis, potentially due to the abundance of oncogenic lncRNAs, such as DUXAP8 and H19, associated with tumor progression." (PMID 37670949, 2023). "Analysis of the relationship between DUXAP8 expression and clinicopathological characteristics revealed that elevated DUXAP8 expression was significantly associated with larger tumor size, more advanced tumor stage, and more lymph node metastasis." (PMID 36329030, 2022). "This study included an in-depth analysis of DUXAP8 expression levels, as well as the relationship with tumor mutational burden (TMB), microsatellite instability (MSI), DNA methyltransferases (DNMTs), and mismatch repair (MMR)." (PMID 36046244, 2022). "Assessment of the MIR4435-2HG/hsa-miR-1-3p/MMP9/hsa-miR-29-3p/DUXAP8 ceRNA network axis in HCC showed that a high risk/poor prognosis was significantly correlated with tumor stage and invasion depth." (PMID 35201491, 2021). "High DUXAP8 expression is closely associated with advanced tumor stages, larger tumor sizes, and metastasis." (PMID 34631702, 2021). "Increased DUXAP8 expression was also found to closely associate with larger tumor size, advanced stage, and shorter overall survival time." (PMID 34631702, 2021). "DUXAP8 was found to be positively related to the tumor stage in neuroblastoma and is negatively associated with patient survival rate." (PMID 34947885, 2021). "High expression of DUXAP8 was associated with advanced tumor stages, larger tumor sizes, lymph node metastases, and poor prognosis." (PMID 34631702, 2021). "Chi‐squared test showed that high expression of DUXAP8 was significantly associated with larger tumor size (P = .0227), TNM stage (P = .0072), and distant metastasis (P = .0018)." (PMID 32022476, 2020). "Moreover, recent studies have shown that increased levels of DUXAP8 in liver cancer are associated with more aggressive tumor characteristics and poorer patient outcomes." (PMID 41362671, 2026). "Additionally, a higher level of DUXAP8 expression in GC was significantly associated with greater tumor size, advanced clinical stage, and lymphatic metastasis." (PMID 28881724, 2017). "Furthermore, we utilized Spearman’s correlation analysis to explore the correlation between DUXAP8 and tumor mutational burden (TMB), microsatellite instability (MSI), the related genes of mismatch repair (MMR), DNA methyltransferases (DNMTs), and immune checkpoint biomarkers." (PMID 36046244, 2022). "This is largely because DUXAP8 contributes to resistance against the drug sorafenib and enhances the proliferation, migration, and invasion of tumor cells." (PMID 41362671, 2026). "CRISPR-mediated DUXAP8 silencing reduces xenograft tumor growth by 72%, validating its therapeutic candidacy." (PMID 40787450, 2025). "Mechanistically, the pseudogene DUXAP8 in non‐small cell lung cancer (NSCLC) represses tumor suppressors EGR1 and RHOB by recruiting histone demethylase LSD1 and histone methyltransferase EZH2, promoting cell proliferation, migration, and invasion." (PMID 40556338, 2025). "Unexpectedly, DUXAP8 showed higher expression levels only in Caki-1 cell lines which indicates the effect of tumor heterogeneity in cancer cells." (PMID 37891201, 2023). "In the present study, we found that the expression level of DUXAP8 in HCC tumor tissue was significantly higher than in adjacent benign tissue using data from TCGA database and the tissue samples of HCC patients diagnosed at our hospital." (PMID 37337470, 2023). "Tumor cell migration and proliferation were facilitated by DUXAP8, CDKN2B-AS1, and MCM3AP-AS1 in HCC." (PMID 37980163, 2023).
tumor (continued). "The difference in DUXAP8 expression level between tumor and non‐tumor tissues was also confirmed by qRT‐PCR assay using 20 pairs of matching HCC and adjacent non‐tumor tissue samples." (PMID 37337470, 2023). "In vitro, we showed that DUXAP8 expression enhanced tumor cell proliferation, migration, and invasion, and promoted HCC progression." (PMID 37337470, 2023). "In this study, we demonstrated that DUXAP8 is a principal modulator of tumor occurrence and advancement in CC." (PMID 35287542, 2022). "DUXAP8 is significantly overexpressed in cancer tissues compared to nearby non-tumor tissues, according to observations." (PMID 36046244, 2022). "Four necroptosis-associated lncRNAs, POLH-AS1, DUXAP8, AC131009.1, and TMCC1-AS1, were used to predict prognosis and attempt to determine tumor immunophenotype." (PMID 35911976, 2022). "Many researchers have investigated public RNA sequencing data and microarray gene profiling data from RCC patients, and found that DUXAP8 was markedly upregulated in RCC tumor tissues compared with adjacent para-tumor tissues." (PMID 34631702, 2021). "Mechanically, RCN2 overexpression markedly reversed the anti-tumor effects induced by miR-1297 overexpression and DUXAP8 knockdown on CC cells, indicating that DUXAP8 regulated the progression of CC by targeting miR-1297/RCN2 axis." (PMID 34774078, 2021). "It was found that DUXAP8 was significantly upregulated in a patient-derived xenograft tumor model based on sorafenib treatment, which is usually associated with a relatively poor prognosis in patients." (PMID 34957112, 2021). "DUXAP8 expression is markedly upregulated in HCC tumor tissues compared to that in corresponding normal tissues." (PMID 34631702, 2021). "MMP9 and two lncRNAs (MIR4435-2HG and DUXAP8) were highly expressed in HCC and were associated with a poor prognosis in patients with HCC and with immune tumor cell infiltration." (PMID 35201491, 2021). "In summary, our results elucidated that that DUXAP8 promoted tumor progression in LUAD by targeting miR-26b-5p, which provide a novel therapeutic target for diagnosis and therapy of LUAD." (PMID 33269379, 2021). "DUXAP8 is frequently dysregulated in multiple cancers, acting as a sponge to downregulate various tumor-suppressing microRNA activities." (PMID 34631702, 2021). "Using an in vivo xenograft tumor model, the regulatory functions and mechanisms of lncRNA DUXAP8 in the progression and response of HCC to chemotherapy were explored." (PMID 34957112, 2021). "The results showed that the expression value of DUXAP8 increased in tumor tissues when compared with their paired normal tissues." (PMID 33318305, 2020). "The mechanisms of DUXAP8 regulation of tumor progression have been shown to differ in different types of human cancers." (PMID 32849765, 2020). "We found that DUXAP8 and its PCGs are differentially expressed in the liver and overexpressed in tumor tissues." (PMID 32922554, 2020). "In this study, we found that lncRNA DUXAP8 was upregulated in tumor samples and served as an oncogene in HCC." (PMID 32849765, 2020). "In summary, we report that lncRNA DUXAP8 was upregulated in tumor samples and served as an oncogene in HCC." (PMID 32849765, 2020). "Except MALRD1, DUXAP8 and the other 9 PCGs were differentially expressed between tumor and non-tumor tissues." (PMID 32922554, 2020). "Elsewhere, DUXAP8 was found to be highly expressed in esophageal squamous cell cancer (ESCC) tissues and was associated with tumor stage, lymph node metastasis, and correlated with poor survival of ESCC patients." (PMID 32922554, 2020). "The results indicated that LncRNA DUXAP8 overexpression significantly promoted the A549 cells’ proliferation, enhanced invasion and induced tumor growth." (PMID 33817152, 2019). "LncRNA DUXAP8 overexpression significantly promoted the cells’ proliferation, enhanced invasion, and induced tumor growth." (PMID 33817152, 2019).